CD4 (CD4 molecule)
Diseases named in the same sentence as CD4 in open-access papers (continued):
Sharing a sentence is not in itself a finding about the gene and the disease.
tumor (continued). "IFN-γ is a pro-inflammatory cytokine released from tumour suppressor cells, such as CD8+ cytotoxic T lymphocytes and CD4+ T cells, and suppresses angiogenesis in the tumour microenvironment (TME), kills pathogens, and stimulates adaptive immunity." (PMID 34291357, 2021). "Abrogating TGFβ signaling in TGFBR2-deleted CD4 T cells inhibited tumor growth by reorganizing the reticular vessel system in tumors." (PMID 34804029, 2021). "In murine PDAC models, oncolytic viruses have demonstrated the capacity to reduce tumor burden and prolong survival by downregulating TAMs and increasing infiltration and function of Th1 CD4+ cells and CD8+ T cells." (PMID 34439292, 2021). "In the animals that overexpressed CTSS or the mutant CTSS, CD8+ T cells were prone to be eliminated and CD4+ T cells were highly infiltrated and colocalized with tumor B cells." (PMID 34069564, 2021). "In contrast, both tumours were equally infiltrated with CD4+ T cells, which included similar percentages of CD44+CD62Lneg cells." (PMID 34471106, 2021). "Patients with a favourable gut microbiota demonstrated increased density of CD8 + cytotoxic T cells and CD4 + regulatory T cells (Tregs) in the tumour microenvironment." (PMID 34302062, 2021). "Then it came to a conclusion that the Foxp3+/CD4+ TIL ratio in tumor tissue was an independent prognostic factor for HCC." (PMID 34566989, 2021). "CD4+ T cells outperformed other leukocytes and provided added predictive value in comparison to age, sex, and tumor stage." (PMID 34204621, 2021). "In the transition from plaque MF to tumor MF, exhausted CD4+ T cells exhibited the most dramatic increase in ligand–receptor interactions of 122%." (PMID 34885092, 2021). "TLR signaling affects the differentiation and function of different T-cell subsets and can directly reverse the suppressive function of tumor-derived CD4+, CD8+, and γδ Treg cells." (PMID 34209514, 2021). "MHC-II is expressed by antigen-presenting cells or tumor cells, presenting exogenously derived peptide antigens to CD4+ T cells." (PMID 34754620, 2021). "Cancer tissues produce large amounts of transforming growth factor beta (TGF-β), which promotes the generation of Foxp3+ Tregs from naïve CD4+ T cells in the local tumor microenvironment." (PMID 34248973, 2021). "The deletion of Tregs from PyMT tumors enables a CD4+ T cell–dependent increase in inflammatory M1-like macrophage infiltration into the tumor-inducing spontaneous tumor immunity." (PMID 34283809, 2021). "Treg cells are a subtype of CD4+ T cell that are critical to the maintenance of immune homeostasis and are involved in tumor immune escape, thereby contributing to tumor development and progression." (PMID 34541005, 2021). "Our results showed that the frequency of Tregs in the group of IL-21high/PD-L1high tumor explants + CD4+ T cells was higher than that of the group of IL-21low/PD-L1low tumor explants + CD4+ T cells (38.8 ± 8.5% vs. 25.8 ± 2.4%, respectively, P < 0.05)." (PMID 34026621, 2021). "The compound also reduced tumor growth in vitro and in tumor-bearing mice by decreasing CD4+CD25+ Treg cell migration and reducing the suppressive function of effector T cells." (PMID 33628720, 2021). "We, and others, have nonetheless shown that circulating CD4 T cells specific for tumor antigens (Ags) are detectable in patients bearing Ag+ tumors." (PMID 33332284, 2021). "The results showed that BTN3A1 expression was negatively associated with tumor purity and positively correlated with infiltration levels of B cells, CD8+ T cells, CD4+ T cells, macrophages, neutrophils, and dendritic cells." (PMID 34293829, 2021). "We observed that the level of CA153 in the blood was positively correlated with the densities of CD3+ and CD4+ TILs in the tumor microenvironment, and the same tendency for CD8+ TILs was observed." (PMID 33718143, 2021).
tumor (continued). "In some studies, it has been reported that PD1:PDL1 binding is also responsible for the conversion of naïve CD4+T cells to Treg cells, which further inhibit the anti-tumor T-cell responses." (PMID 34485117, 2021). "Taken together, our data indicate that ex vivo activation of tumor-primed CD4+T cells with high salt resulted in a strong anti-cancer response with a strong futuristic possibility to adopt similar human cell-based immunotherapeutic approaches." (PMID 33918403, 2021). "With the data collected from The Cancer Genome Atlas (TCGA), we evaluated the association of KEAP1 mutation with tumor infiltrating leukocytes (TILs), including dendritic cell, CD8 T cell, CD4 T cell, neutrophil, B cells, and macrophage." (PMID 34328274, 2021). "Meanwhile, memory CD4+ T cells inhibit the outgrowth of tumor cells by promoting the proliferation of CD8+ cells." (PMID 34888385, 2021). "These experiments were performed with the total CD4+ T cell population as we felt this better reflected the CD4+ T cell populations within the tumour and so potentially lead to a more predictive response." (PMID 33597595, 2021). "In conclusion, we show that our heterologous prime-boost vaccination inducing cross-presenting cDC1s and CD4+ T cells convey a potent anti-tumor CD8+ T-cell response in both immune excluded and infiltrated mouse cancer models." (PMID 34885215, 2021). "PD-1 is upregulated on CD8+ and CD4+ T cells during pathogen- or tumor-induced activation, serving to limit the activity of T cells." (PMID 34571982, 2021). "DC vaccines activate the immune functions of CD8 and CD4 T lymphocytes by loading tumor peptides and eliminate tumor cells." (PMID 34123855, 2021). "Recent clinical evidence has also raised the importance of CD4+ T cells in generating successful anti-tumour immunity." (PMID 32457487, 2021). "Th17 is a specific subset of CD4 T cells characterized by higher secretion of IL-17 and other inflammatory cytokines and plays a dual role in tumor promotion and suppression." (PMID 33808190, 2021). "The frequencies of CD8+ T cells (CD45+ CD3+ CD11b- CD4- CD8+) and Foxp3-CD4+ T cells (CD45+ CD3+ CD11b- CD4+ CD8- Foxp3-) in CT-26 tumor tissues were significantly higher than those in Colon 26 tumor tissues." (PMID 34774008, 2021). "Previous studies have reported that the number and functional orientation of tumor-infiltrating CD4+ and CD8+ T cells and the presence of M1 type macrophages strongly correlates with survival in patients with CC after CRT23,24." (PMID 33619320, 2021). "Studies using the A20 B‐cell lymphoma cell line and the B16 melanoma cell line showed that antigen secretion by tumor cells and the indirect presentation of antigen‐presenting cells play key roles in the rejection of tumor cells by CD4+ T cells." (PMID 33657268, 2021). "We found a significant increase in both CD8+ T cell and CD4+ Teff cell to Treg cell ratios within tumor in anti-LILRB4–treated mice." (PMID 33974041, 2021). "Despite their theoretical capability of inducing strong anti-tumor T-cell responses and priming CD4+ and CD8+ T-cells against tumor antigens, pDC infiltration is found to be associated with poor prognosis in several solid tumors." (PMID 34483843, 2021). "On the basis of their gene expression profile tumor-infiltrating CD4+ TC accumulated into five well-separated clusters defined by the expression of 1662 significant marker genes (P < 0.05, cluster 0:154, 1:546, 2:58, 3:114, 4:790)." (PMID 33602930, 2021). "In spleens of tumor-bearing mice, chemotherapy down-regulated CD4+ TNFR2+ FOXP3+ cells but the subset of CD8+ TNFR2+ PD-1+ was not present prior to chemotherapy and was not increased by the treatment." (PMID 34201054, 2021). "We demonstrate for the first time that tumor location has a significant impact upon the prognostic utility of CD4+ and CD8+ TILs in HNSCC." (PMID 33668519, 2021).
tumor (continued). "Interaction of PD-L1 on tumor cells with PD-1 on tumor-specific T cells promotes differentiation of naïve CD4+ T cells into Tregs, leading to immune suppression that supports tumor growth." (PMID 35250965, 2021). "CD8+ T cells infiltrated the tumor stroma, invasive margin, and center, whereas CD4+ and Foxp3+ T cells mainly infiltrated the tumor stroma and invasive margin." (PMID 35087741, 2021). "IL-21, produced predominantly by activated CD4+ T cells, has been reported to promote T cell-mediated tumor rejection and has pleiotropic effects on immunity via the IL-21 receptor." (PMID 34853180, 2021). "Though not reaching statistical significance, we observed a trend consistent with biased expression of LAIR2 as seen in scRNASeq data and found a 2-fold higher secretion of LAIR2 by tumor infiltrating CD4+ T cells than CD8+ T cells." (PMID 35008369, 2021). "(C) Flow cytometric analysis of the frequencies of Foxp3+ cells among CD4+ T cells in the tumor (n = 11 in each group) and draining lymph node (n = 8 in each group) in Cd300afl/fl and Cd300afl/fl;ItgaxCre mice." (PMID 34751648, 2021). "Compared to the control group, in the cGAMP@dual-anti-Exos treatment group, CD8+ and CD4+ T cells remarkably infiltrate tumor issues." (PMID 34541546, 2021). "We observed that there is very high individual variability in DNA methylation pattern of these genes (promotor and intragenic regions) in GBM tumor infiltrating CD4+ T cells." (PMID 34012510, 2021). "With the common termination point for the curves at Cluster CD4_4, we next wanted to examine if there are common markers for CD4+ T-cell infiltration in ccRCC by comparing tumor-infiltering to peripheral-blood CD4+ T cells." (PMID 33504936, 2021). "Although this trial did not allow correlation with clinical outcome, it did show that CD4+ T cells from blood and tumor tissue of all treated patients increased the expression of ICOS and the production of IFN-γ." (PMID 33777008, 2021). "MiR-155 has been also shown to regulate adaptive immunity by promoting IFNγ anti-tumor responses by CD4+ and CD8+ T-cells." (PMID 33924670, 2021). "The frequency of CD8+ and CD4+ T cells in tumor microenvironment (TME) and spleen was assessed via flow cytometry." (PMID 33981600, 2021). "The tumor immune microenvironment consisted of massive immune cell subsets surrounding cancer cells, including B cells, CD4+ T cells, CD8+ T cells, neutrophils, macrophages, and dendritic cells." (PMID 34220923, 2021). "Tumor-infiltrating CD4+ and CD8+ T-cells were also identified and evaluated for different markers of activation." (PMID 34503272, 2021). "CD4 T cells can promote anti-tumor immunity by supporting the priming, migration, and survival of CD8 T cells." (PMID 34502325, 2021). "These activated dendritic cells are then able to stimulate both CD8 T cells, in addition to helper CD4 T cells and/or natural killer cells, as the tumor protection resulting from ILV/mIL12 administration was lost when these populations were depleted." (PMID 34855754, 2021). "The model variable for activated T cells (ATC) was found to be highly sensitive throughout the treatment period (days 22, 112, 147) for Patient 1–5, to parameter c4 (maximum CD4+ T cell production rate stimulated by the interactions with tumor cells)." (PMID 34559809, 2021). "In BC, CD4+ T cells infiltration in the tumor microenvironment positively correlates with decreased OS." (PMID 34220957, 2021). "Removing CD25+CD4+ T cells or in vivo administration of anti-CD25 monoclonal antibody in mice can induce tumor immunity or tumor suppression." (PMID 34824364, 2021). "By secreting the suppressive cytokines IL-10, IL-35 and TGF-β, Bregs suppress CD4+ T cell proliferation and promote Foxp3 expression in Tregs, thereby favoring immunosuppression and tumor development." (PMID 34681881, 2021).
tumor (continued). "Within the cancer context, multiple lines of evidence point to the importance of CD4+ T cell recognition of tumor antigens for responses to cancer immunotherapy." (PMID 34910940, 2021). "Prime-boost treatment reduced tumor-infiltrating regulatory CD4+ T cells whilst increasing cross-presenting dendritic cells in tumor-draining lymph nodes." (PMID 34885215, 2021). "Herein, the recent research progress on tumor‐infiltrating B cells and T cells, including CD8+ T cells, CD4+ T cells, and exhausted T cells and their role in anti‐tumor immunity, is summarized." (PMID 34658167, 2021). "When stimulated in vitro, these CD4+ memory T cells were able to recognize a neoantigen specific to that patient’s tumor." (PMID 34483843, 2021). "The T cell membrane OX40 binds to OX40L on DC and induces a phenotypic subtype of CD4+ T cells, promoting tumor growth." (PMID 33986746, 2021). "A recent report showed that cancer-derived sialylated IgG in the tumor microenvironment can promote tumor immune escape by binding to Siglecs on effector CD4+ and CD8+ T cells." (PMID 33921986, 2021). "This is true especially for cancer treatment, as CD4+ T cells have opposing effects on tumor growth and response to immunotherapies, crucially depending on the CD4 effector cell differentiation and tumor entity." (PMID 34956237, 2021). "Previous clinical studies confirmed that a tumor antigen-derived peptide vaccine can induce T cell activation and promote the infiltration of CD4+ and CD8+ T cells to kill antigen-expressing tumor cells." (PMID 34384429, 2021). "We also observed a weak, but significant inverse correlation between the frequency of tumor-infiltrating CD4+ T cells and the sensitivity status of the tumors." (PMID 34868026, 2021). "The results indicate that IFN-γ plays a direct or indirect role in the recruitment of CD8+CXCR3+ and CD4+CXCR3+ T cell subsets into SCC tumours." (PMID 33925140, 2021). "Although cytotoxic (CD8+) T cells are a direct component of anti-tumor immunity, CD4+ T lymphocytes provide not only an auxiliary function of signal presentation, but also a core function by changing the tumor microenvironment." (PMID 34327142, 2021). "The expression level of S100P was negatively correlated with B cells, CD8+ T cells, CD4+ T cells, neutrophils, and dendritic cells but positively correlated with tumor purity in LUAD." (PMID 34745947, 2021). "Multiplexed immunofluorescence staining of tumor tissue revealed an increased infiltration of CD4+ and CD8+ T cells upon therapy." (PMID 33275172, 2021). "SHH MB subgroup has increased expression of inflammation-related genes (CD14, PTX3, CD4, CD163, CSF1R, and TGFB2) and significantly higher infiltration of tumour-associated fibroblasts than Grp3 MB and Grp4 MB." (PMID 34195095, 2021). "Labelling and gating strategies were developed to quantify tumour infiltrating lymphocytes (TILs) (CD3/CD4/CD8/CD19) and myeloid lineage cells (CD45+/CD11b+; macrophages: CD11b+/Ly6GlowF4/80+; neutrophils: CD11b+/Ly6Ghi; and dendritic cells CD11b+/CD11c+)." (PMID 34242269, 2021). "Overall, our data demonstrate that therapeutic transfer of ex vivo-generated act-A-CD4+ T cells to LLC-OVA-bearing CD4−/− mice leads to a marked reduction in tumor burden of recipients and protects against disease progression." (PMID 34548096, 2021). "CD4+ T lymphocytes can help in anti-tumor immunity by aiding pro-inflammatory antigen-presenting cells and supporting cytotoxic CD8+ T lymphocytes." (PMID 34947972, 2021). "Tumor infiltrating lymphocytes (TILs), especially the infiltration of CD4+ GzmB+ T cells in the central region of the tumor was identified to be positively correlated with the prognosis of the patients." (PMID 34631551, 2021). "Altogether, the upregulated expression of Ki67, IFNγ, CD25, and CD27 among the CD8 and CD4 T-cell clusters indicate that the large tumors in the PD-1cKO are highly immunogenic with a potential for tumor regression, evident at later time points." (PMID 34912335, 2021).
tumor (continued). "Tumor samples were immunohistochemically analyzed for expression of PD-L1, CD4, and CD8, and further investigated by transcriptome analysis." (PMID 34572789, 2021). "Since primary role of CD4+ T-cells is to orchestrate a lineage specific immune response against pathological antigens, we looked for specific CD4+ T cell sub-population signatures in the tumor infiltrating CD4+ T cells." (PMID 34012510, 2021). "IL-2 and IFNγ (Interferon) producing CD4 T cells such as Th1 have been shown to play an essential role in the induction and persistence of anti-tumor CD8 T cells." (PMID 33498483, 2021). "Systemic BEMPEG treatment‐driven increase in the ratio of CD4+ effector to CD4+ regulatory T cells was most prominent in the tumor‐bearing lungs." (PMID 33152115, 2021). "Two-way ANOVA revealed a significant interaction between age and stress status (p=0.02) in tumor CD4+FoxP3+ cells number." (PMID 34604038, 2021). "A subgroup of CD4+T cells, referred to as Treg cells can inhibit anti-tumor immune response and mediate tumor immune escape." (PMID 34880875, 2021). "The upregulation of PD-L1 signifies a poor prognosis in NSCLC because it negatively regulates levels of CD4+ and CD8+ tumor-infiltrating T lymphocytes, which are associated with a better prognosis." (PMID 34433810, 2021). "Our results suggest that exhausted CD8+ T cells and CD4+ Tregs in tumors likely evolved from other types of CD8+ and CD4+ T cells inside the tumor." (PMID 33513276, 2021). "When immature DCs recognize, uptake, and cross-present the antigens released by tumor cells, they shift to secondary lymphoid organs, where they activate CD4+ T cells or CD8+ T cells to trigger specific CTLs responses against target cells." (PMID 34805170, 2021). "Tumor-infiltrating CD4+ T cells and CD8+ T cells from mice given low-dose TSA treatment had an increased frequency of TNF-α and IFN-γ producers compared with vehicle treatment group." (PMID 33564072, 2021). "Compared with tumor-bearing Mφs, cryo-thermal Mφs promoted the differentiation of CD4+ T cells to CD4 CTLs and reduced the percentage of Tregs, while the percentages of Th1, Tfh, Th2 and Th17 cells were not changed." (PMID 34209797, 2021). "We suggest that, similar to CD8 TILs, CD4 T cell exhaustion at the tumor site is instated in tumor Ag–specific T cells as a result of chronic exposure to the Ag." (PMID 33332284, 2021). "Whereas the important role of CD8 + CTLs in anti-tumor immune response has been known for many years, the potential importance of CD4 + Th cells in the generation and maintenance of anti-tumor activity has only recently been reported." (PMID 33761971, 2021). "In a mouse model of PDAC, the same vaccine induced protective immunity characterized by the expansion of effector and memory CD8+ T cells, CD4+ T cells (excluding Treg cells), and B cells, while reducing the amount of Treg cells in tumor-draining lymph nodes." (PMID 34830945, 2021). "MHC-II–restricted neoantigens recruit tumor-specific CD4 T cells to tumor sites, subsequently promoting optimal priming and generation of CD8 cytotoxic T lymphocytes to eliminate tumor cells." (PMID 34290401, 2021). "When validating these data, the authors demonstrated that these tumor-specific CD4+ T cells are able to kill tumor cells by a direct contact and granzyme-dependent mechanism, but with a delayed kinetic when compared to a more classical CTL." (PMID 34386013, 2021). "Early reports as far back as 2009 indicated potential involvement of FoxP3+ CD4+ Tregs in the anti-tumour response in patients that had been treated with a MHC II-restricted MAGE-A3 peptide vaccine." (PMID 32457487, 2021). "This is evidenced by a significant increase in TILs as well as a decrease in the proportion of CD8 T cells to CD4 T cells observed in IDC tumours in comparison to DCIS tumours." (PMID 33794894, 2021). "Among the total CD3+ T lymphocytes, the proportion of CD4+ T cells was about 36% in the stroma, and less than 20% within the tumor mass." (PMID 34944746, 2021).